TMEM255A (transmembrane protein 255A)
Synonyms: FAM70A; FLJ20716
Tractability: Antibody: UniProt predicts a signal peptide or a membrane-spanning region.
Gene: Protein-coding gene on chromosome X (120,258,650 to 120,311,556, reverse strand). Ensembl gene ENSG00000125355.
Subcellular location: Membrane
Subcellular location (Human Protein Atlas): Nuclear bodies; Nucleoplasm
Gene Ontology:
Cellular component: membrane
Homologues: Orthologues: chimpanzee TMEM255A (100% identical), macaque TMEM255A (99% identical), rabbit TMEM255A (99% identical), dog TMEM255A (98% identical), guinea pig TMEM255A (98% identical), pig TMEM255A (98% identical), mouse Tmem255a (98% identical), rat Tmem255a (98% identical), tropical clawed frog lamp2 (71% identical), zebrafish tmem255a (64% identical).
Diseases named in the same sentence as TMEM255A in open-access papers:
TMEM255A is named in the same sentence as 4 diseases in open-access papers, as found by Europe PMC text mining. Sharing a sentence is not in itself a finding about the gene and the disease. The quoted sentences say what the papers report.
oncocytoma (1 paper, 2017). "The chRCC and oncocytoma samples displayed almost identical gene expression profiles for MAL, TMEM255A, RHCG, ATP6V0A4, STAP1, and DEFB1, as demonstrated by both RNA microarray and RNA sequencing, which is in agreement with the known fact that chRCC and oncocytoma are related neoplasms." (PMID 29208006, 2017).
cancer (2 papers, 2012 to 2024). A tumor composed of atypical neoplastic, often pleomorphic cells that invade other tissues.
TMEM255A also shares sentences with these, for which no sentence is quoted: neoplasm (2 papers); melanoma (1).